TLR2 (toll like receptor 2)
Diseases named in the same sentence as TLR2 in open-access papers (continued):
Sharing a sentence is not in itself a finding about the gene and the disease.
pneumococcal meningitis (16 papers, 2007 to 2026). An acute purulent infection of the meninges and subarachnoid space caused by Streptococcus pneumoniae, most prevalent in children and adults over the age of 60. "On the other hand, polymorphisms of TLRs are involved in the susceptibility to infections; in this context, the TLR2 2477G/A polymorphism contributes to an increased risk of pneumococcal meningitis in the Caucasian population." (PMID 38891900, 2024). "The costimulatory protein B7-H3 contributes to the development and progression of pneumococcal meningitis by augmenting the innate immunity-associated inflammatory response in a TLR2-dependent manner." (PMID 39497833, 2024). "TLR2 rs5743708 polymorphism was present in 4% children with pneumococcal meningitis and 7% of the control group (p = 0.04)." (PMID 29754263, 2018). "The costimulatory protein B7-H3 has been shown to play a contributory role in the development and progression of experimental pneumococcal meningitis by augmentation of the innate immunity-associated inflammatory response via a TLR2-dependent manner." (PMID 28141831, 2017). "The important involvement of TLR2 in pneumococcal meningitis was previously demonstrated in TLR2-deficient mice infected with S. pneumoniae serotype 3, showing an increase in the bacterial load and blood-brain barrier disruption." (PMID 26648922, 2015). "During pneumococcal meningitis strong inflammation in TLR2-deficiency was associated with incomplete responsiveness to antibiotics and complete response to combined antibiotic and TACE inhibitor treatment." (PMID 17428319, 2007). "In a mouse model deficiency of TLR2 increases the severity of the pneumococcal meningitis." (PMID 29754263, 2018). "Our study indicates the importance of murine TLR13 and human TLR8, besides TLR2, in pneumococcal meningitis pathology, and suggests their blockade as a promising antibiotic therapy adjunct." (PMID 38358825, 2024). "In our search for additional treatment options, we recently employed a neutralizing TLR2 and -4 specific antibody cocktail in an experimental murine pneumococcal meningitis study." (PMID 38358825, 2024). "TLR2 and TLR13 play essential roles in experimental pneumococcal meningitis pathology, suggesting TLR2/TLR13 blockade as a promising adjunctive therapy for antibiotics." (PMID 38358825, 2024). "B7-H3 plays a role in S. pneumoniae infection-induced pneumococcal meningitis by amplifying the inflammatory response, worsening blood-brain barrier disruption, and aggravating the clinical disease status via a TLR2-dependent mechanism." (PMID 39497833, 2024). "Accordingly, TLR2/TLR13 blockade concomitant with ceftriaxone application significantly improved the clinical course of pneumococcal meningitis compared with treatment with ceftriaxone alone or in combination with dexamethasone." (PMID 38358825, 2024). "First, we comparatively monitored the course of experimental pneumococcal meningitis in WT, Tlr2/4–/–, Myd88–/–, and 3d/Tlr2/4–/– mice." (PMID 38358825, 2024). "CXCL16 was dependent on TLR2/4 and MyD88 signaling for neutrophil recruitment in the cerebrospinal fluid of patients and mice with pneumococcal meningitis." (PMID 37160878, 2023). "In pneumococcal meningitis, the interaction of TLR2 and TLR4 is required for the immunologic reaction." (PMID 31791382, 2019). "Significantly upregulated TLR2 mRNA expression was also detected in the brain of S. pneumoniae infection-induced experimental pneumococcal meningitis." (PMID 28141831, 2017). "This study aimed to clarify the component(s) of TLR2-mediated signal transduction pathways responsible for B7-H3-augmented inflammatory response and subsequent brain damage during experimental pneumococcal meningitis." (PMID 28141831, 2017). "Toll-like receptor 2 (TLR2) contributes to host response in pneumococcal meningitis by enhancing bacterial clearing and downmodulating inflammation." (PMID 17428319, 2007).
pneumococcal meningitis (continued). "Given the apparent need for more potent adjunctive treatments, we investigated whether mice with antibiotic-treated pneumococcal meningitis would benefit from concurrent TLR2 and -13 blockade." (PMID 38358825, 2024). "We and others found accelerated mortality of TLR2-/-mice with pneumococcal meningitis." (PMID 17428319, 2007). "Thus, it appears possible that expression of CCL20 is mediated by TLR2 and TLR4 activation during pneumococcal meningitis." (PMID 24699535, 2014). "This study has compared outcome and treatment effects of antibiotics and TACE inhibitor TNF484 during pneumococcal meningitis in mice lacking the pattern recognition receptors TLR2 and/or CD14." (PMID 17428319, 2007). "Consequently, combining antimicrobial therapy with TLR2- and endosomal TLR–specific antagonists effectively protected mice from pneumococcal meningitis pathology and significantly inhibited S. pneumoniae–induced activation of murine macrophages and human PBMCs in which TLR8 substitutes for TLR13." (PMID 38358825, 2024). "In a murine model of pneumococcal meningitis, B7-H3 could augment pro-inflammatory cytokine and chemokine production, upregulate NF-κB p65 and MAPK p38 phosphorylation, and enhance the nuclear transactivation of NF-κB p65 through TLR2-dependent mechanism." (PMID 27188891, 2016). "Previous analyses of mice lacking expression of single or multiple TLRs such as TLR2, -4, and/or -9 suggested involvement of all 3 in S. pneumoniae–induced immune cell activation in vitro as well as in pneumococcal pneumonia, but only of the first 2 in pneumococcal meningitis." (PMID 38358825, 2024).
diabetic nephropathy (15 papers, 2013 to 2025). "Activation of the innate immune system and induction of pro-inflammatory cascade via TLRs, specifically TLR2 and TLR4, has been implicated in the pathogenesis of diabetic nephropathy." (PMID 40584714, 2025). "APOC3, which plays a multifaceted role in triglyceride homeostasis, has been reported to exacerbate early-stage diabetic nephropathy by activating the renal TLR2/NF-κB pathway." (PMID 41438111, 2025). "What’s more ApoC3 overexpression aggravated early-stage diabetic nephropathy by activating the renal TLR2/NF-κB pathway with increased renal inflammation in mice." (PMID 37689737, 2023). "The present study aims to examine the renal SGLT2 induction by the TLR2/4 ligand Porphyromonas (P.) gingivalis lipopolysaccharide (Pg-LPS) in mouse diabetic nephropathy." (PMID 34425759, 2021). "Preclinical evidence supported the concept that TLR2 and/or TLR4 are causative in diabetic kidney disease (DKD; Panchapakesan and Pollock, 2018)." (PMID 33442388, 2020). "We and others have also shown evidence for TGFβ induced activation of the innate immunity pathway in diabetic nephropathy, in particular Toll like receptor 2 (TLR2) and its endogenous ligand High Mobility Group Box 1 (HMGB1)." (PMID 25369239, 2014). "Literature data from recent years indicate that an important role in diabetic nephropathy etiopathogenesis may be played by signal transduction pathways that are dependent on TLR2, TLR9, and TLR4 receptors." (PMID 32933213, 2020). "The reaction products with anti-TLR2 were also localized at the inside of the diabetic mouse proximal tubules, and it is thought that proximal tubule epithelial cells have the ability to express TLR2 on the luminal side under the condition of diabetic nephropathy." (PMID 24835775, 2014). "The present study aimed to examine the TLR2 expression in glomerular endothelial cells in diabetic mice and the effect of LPS from the periodontal pathogen Porphyromonas gingivalis on the progress of diabetic nephropathy." (PMID 24835775, 2014). "Furthermore, the levels of other inflammation-associated receptors (e.g., TLR2, TLR4, and RAGE) were elevated in diabetic nephropathy kidney tissue, together with DAMPs, such as AGEs, HMGB1, HSP70, and S100 calgranulins (e.g., S100A8 and S100A9), triggering their activation." (PMID 33478014, 2021). "The study here investigates the effects of the periodontal pathogen Porphyromonas gingivalis lipopolysaccharide (LPS) which is a ligand for TLR2 and TLR4 in diabetic nephropathy." (PMID 24835775, 2014). "In the human kidney samples with diabetic nephropathy, there were PECAM-1-positive glomerular endothelial cells reacted with both anti-PECAM-1 and anti-TLR2, and cells only immunostained with anti-TLR2." (PMID 24835775, 2014). "HMGB1 is a known ligand of advances glycation end products receptor (RAGE), as well as Toll-like receptor 2 (TLR2) and TLR4, which are involved in the inflammatory process of diabetic nephropathy leading to NF-κB activation." (PMID 24089613, 2013). "Mudaliar H also revealed that TLR2 and TLR4 promote inflammation in diabetic nephropathy through activation of NF-κB, and their inhibition may be a new therapeutic target." (PMID 40584714, 2025). "TLR4 expression was increased in macrophages of diabetic nephropathy patients, while TLR2 expression was not changed." (PMID 37538798, 2023). "These may suggest that Pg-LPS-induced diabetic nephropathy is mainly dependent on TLR2 signaling on glomerular endothelial cells, and that TLR4 blocker eritoran may play a role to slow the progress of diabetic nephropathy." (PMID 29018490, 2017). "However, our data strongly supports the role of both TLR2 and 4 in regulating vascular inflammation via ICAM-1 expression in an in vivo model of diabetic nephropathy." (PMID 25303153, 2014). "Although the literature data indicate a key role of TLR2 and TLR4 in the pathophysiology of diabetic nephropathy, the participation of other receptors is not excluded." (PMID 32933213, 2020).
diabetic nephropathy (continued). "Similarly, in vivo data showed an increase in tubular TLR2, HMGB1, and fibronectin expression, with no increase in TLR4 expression, suggesting that the HMGB1-TLR2-NF-κB pathway might play a dominant role in mediating inflammation in diabetic nephropathy in the long term." (PMID 40584714, 2025).
eosinophilia (15 papers, 2013 to 2024). "Airway hyper-responsiveness (AHR) and BAL eosinophilia were unaffected by FSL-1 treatment in TLR2-deficient mice, thus confirming the effect of FSL-1 was dependent upon TLR2." (PMID 39273551, 2024). "Specifically, the exacerbative effects of LPS and H-ASD on OVA-induced lung eosinophilia were investigated using wild-type (WT), TLR2−/−, TLR4−/− and MyD88−/− mice with BALB/c background." (PMID 31889961, 2019). "Secondly, the lung eosinophilia was more severe in TLR2−/− mice than in TLR4−/− mice, probably due to the fact that TLR2 is not involved in the immune response to LPS." (PMID 31889961, 2019). "Addition of eLPS during Bt sensitization resulted in inhibition of airway eosinophilia in WT and also in CD14−/−, TLR4−/− and TLR2−/− mice, suggesting that these molecules are dispensable for the inhibition of airway eosinophilia induced by eLPS." (PMID 23805294, 2013). "We observe a decreased AHR and lung eosinophilia in mice that received prior treatment with the TLR-2 agonist." (PMID 23393567, 2013). "Urban PM2.5 containing trace microbial elements may exacerbate allergic inflammation and eosinophilia in the murine lung via a TLR2/TLR4/MyD88-signaling pathway." (PMID 33809902, 2021). "Furthermore, we have shown that co-exposure to B. adusta and H-ASD exacerbated lung eosinophilia via the TLR2 signaling pathway." (PMID 27766108, 2016). "However, at prolonged periods after withdrawal of the TLR-2 agonist, lung eosinophilia and AHR were both effectively suppressed upon allergen challenge (protocol 2)." (PMID 23393567, 2013). "This novel finding built upon the authors previous research that established LPC signaling through TLR2 mediates eosinophil recruitment and function during S. mansoni infection, whereby TLR2 deficient mice lacked strong type-2 immunity and blood/tissue eosinophilia." (PMID 31134080, 2019). "Finally, in OVA-sensitized BALB/c mice, TLR2/6 intratracheal administration before OVA challenge significantly decreased BAL IL-5 and IL-13 but increased BAL eosinophilia." (PMID 39273551, 2024). "After demonstrating the relationship between SIgA levels and eosinophils controlling larval migration, and after verifying the increase in the expression of TLR2 and TLR4 in single-infected mice, we assessed the potential role of TLRs in triggering SIgA production and eosinophilia." (PMID 34784389, 2021). "We also assessed the affects of TLR2, TLR4 and MyD88 on eosinophilia in the blood in AAD." (PMID 27309732, 2016). "We found that eLPS did not suppress airway eosinophilia in MyD88- or IFN-γ ̃deficient mice while suppression was observed in mice deficient in CD14, TLR4 or TLR2 molecules." (PMID 23805294, 2013). "Then in AAD we identified inductive roles for: TLR2 in IL-5 release from MLN T cells, IL-5 and IL-13 release from splenocytes and AHR; TLR4 in eosinophil infiltration into BALF and blood (partial) and AHR, and; MyD88 in blood eosinophilia, IL-13 release from MLN T cells and AHR." (PMID 27309732, 2016). "In KSpn-mediated suppression of AAD we identified important suppressive roles for: TLR2 in eosinophil infiltration into the airways (partial) and AHR; TLR4 in eosinophilia of the airways and blood, IL-5 and IL-13 release from splenocytes and AHR, and; MyD88 in airway and blood eosinophilia and AHR." (PMID 27309732, 2016). "The increased expression of TLR2 and TLR4 to the antigen surface of O. occidentalis may contribute to the initiation of immune responses, including Th2-cell responses that generally result in eosinophilia, goblet and mucosal mast-cell hyperplasia, which lead to the elimination of the parasite." (PMID 26622306, 2015). "Here, we found that inhalation of FAP by naïve mice led to airway eosinophilia that was dependent on protease-activated receptor-2 (PAR2), but not TLR2 and TLR4." (PMID 30575775, 2018). "In the absence of TLR2, MLN T cell and splenocyte release of IL-5 were reduced but there was no impact on eosinophilia in the BALF or blood." (PMID 27309732, 2016).
Hepatitis (15 papers, 2014 to 2024). Inflammation of the liver. "However, our results indicate that both synonymous mutation and polymorphism in the promoter of TLR2 were associated with milder hepatitis activity." (PMID 29320990, 2018). "We observed a positive association between TLR2 polymorphisms and hepatitis activity." (PMID 29320990, 2018). "Likewise, in choline-deficient amino-acid- (CDAA-) defined diet-induced NASH models, TLR2 and palmitic acid cooperatively activate the inflammasome in KCs, and TLR2 deficiency showed diminished inflammasome activation and decreased liver inflammation and fibrosis." (PMID 27446858, 2016). "TT genotype of rs3804099/TLR-2 was significantly more prevalent in inactive carriers compared to active hepatitis patients (P = 0.04, OR = 0.39 and 95% CI: 0.16–0.95)." (PMID 35119591, 2023). "Similar to our results, EA was proved to possess a protective effect on concanavalin A-induced hepatitis in mice via decreasing the expressions of TLR2 and TLR4, and suppressing NF-κB signaling pathway." (PMID 35436978, 2022). "It is likely, that innate immune signaling by TLR2 is involved in the hepatitis phase of CHB and is controlled by IL10 in the infection phase." (PMID 32632817, 2021). "Studies looking at the interaction between TLR2 and TLR6 found that deregulation of TLR6 expression potentiated the TLR2-mediated liver inflammation." (PMID 29563854, 2018). "Others have found evidence of increased TLR2 level associated with higher serum ALT concentration and advanced hepatitis activity in an Iranian population." (PMID 29320990, 2018). "With this work, we explored the mechanism by which TQ regulates inflammation using both in vitro (TLR2/3/4-stimulated primary and cancerous macrophages) and in vivo (mouse gastritis and hepatitis models) experimental conditions." (PMID 28216638, 2017). "Thus, it seems likely that such connections existing between TLR2 and hepatitis activity were mediated by the production of pro-inflammatory cytokines." (PMID 29320990, 2018). "This suggestion is in accordance with an analysis of TLR2 responsiveness in PBMCs of a small cohort of HBeAg-positive CHB patients, indicating that TNF and IL6 are induced in the hepatitis phase, whereas IL10 dominates the response in immune tolerant patients." (PMID 32632817, 2021). "Quercetin was shown to reduce the expression of high mobility group box 1 (HMGB1) and the mRNA and protein levels of TLR2 and TLR4 in liver tissues of mice with hepatitis." (PMID 31714944, 2019). "The development of hepatitis was also unaltered by quercetin supplementation; both HFDs increased JNK activation and MCP-1 and TLR2 gene expression relative to the AIN-76A diet (P ≤ .05)." (PMID 27959936, 2016). "AP-1, TLR2, and IL1-β, genes that are differentially regulated during the pathological progression of NASH liver inflammation, and SCD1, LEPR, and other genes related to NASH lipid deposition, were regulated by caffeine, but EGCG had no significant regulatory effect." (PMID 34881283, 2021). "The reduced expression levels of TLR2, TLR4 and TLR9 mRNAs or proteins can enhance protection against T cell-mediated hepatitis in mice, and the reduced expressions of TLR4, MyD88 and NF-κB may mediate the protective effects against LPS through reducing the level of pro-inflammatory cytokines." (PMID 30909396, 2019).